NFATC1 (nuclear factor of activated T cells 1)
Diseases named in the same sentence as NFATC1 in open-access papers (continued):
Sharing a sentence is not in itself a finding about the gene and the disease.
asthma (9 papers, 2019 to 2025). "Here, we sought to investigate the role of NFATc1 and NFATc2 in different cohorts of asthmatic and control children and adults to better understand the distinct role of these two transcription factors and their association with different forms of asthma." (PMID 33079489, 2020). "We next analyzed NFATc1 and NFATc2 mRNA in the PBMCs in the newly recruited cohorts of children one without asthma (control children, n = 7) and the second one with asthma (asthma children, n = 6) at primary school‐age (AGENDAs cohort)." (PMID 33079489, 2020). "It is thus possible that NFATc2 correlates with inflammatory eosinophils whereas NFATc1 correlates with lymphocyte proliferation in asthma." (PMID 33079489, 2020). "In summary, in this paper, we started to analyze the correlation between NFATc1 and NFATc2 in asthma with different cells present in the peripheral blood of children with and without asthma." (PMID 33079489, 2020). "Interestingly, numerous Ca2+-dependent transcription factors like c-FOS, nuclear factor of activated T cell (NFATC1), and cAMP response element–binding protein (CREB1) as well as the asthma-associated protein ORMDL3 were downregulated in the NCLX KD HASMCs." (PMID 35841929, 2022). "Moreover, NFATc1 directly correlated with lymphocytes number whereas NFATc2 correlated with peripheral eosinophilia in asthma." (PMID 33079489, 2020). "NFATc2 mRNA showed a direct correlation with eosinophils both in controls and asthma, indicating that NFATc1 is associated with lymphocytes and not eosinophils in asthma." (PMID 33079489, 2020). "In summary, this study just starts to investigate different roles of NFATc1 and NFATc2 in allergic asthma whereby we found that NFATc2 relates more closely to peripheral blood eosinophils and NFATc1 to lymphocyte proliferation in pediatric asthma." (PMID 33079489, 2020). "Similarly, in asthma, we found only a direct correlation of NFATc1 with lymphocytes in control children and an opposite correlation between NFATc1 and peripheral eosinophils in asthma." (PMID 33079489, 2020). "In asthma, this effect was abolished probably because other transcription factors might replace NFATc1 on T-bet promoter." (PMID 31666531, 2019). "Furthermore, we next asked about a correlation between the recently described increase of NFATc1 in the blood of children with asthma and NIP45." (PMID 31666531, 2019). "Therefore, we speculated that TLR2/NF-κB/NFATc1 pathway may be involved in SREBP2 regulation in asthma." (PMID 35037821, 2022). "Moreover, NFATc1 messenger RNA (mRNA) correlated with lymphocytes both in control and asthma." (PMID 33079489, 2020). "Here, we found that NFATc1 mRNA correlated with lymphocytes both in control and asthma and both NFATc1 and NFATc2 mRNA showed a direct correlation with eosinophils in controls but not in asthma, indicating that NFATc1 is associated with lymphocytes and not eosinophils in asthma." (PMID 33079489, 2020). "Moreover, NFATc1 mRNA correlated with lymphocytes both in control and asthma, and NFATC1 and NFATc2 mRNA showed a direct correlation with eosinophils in controls but not in asthma, indicating that NFATc1 is associated with lymphocytes and not eosinophils in asthma." (PMID 33079489, 2020). "MiR-143-3p inhibits airway remodeling in asthma, suppressing transforming growth factor (TGF)-β1-induced cell proliferation and protein deposition of extracellular matrix (ECM) production proliferation via negative regulation of nuclear factor of activated T cells 1 (NFATc1) signaling." (PMID 36612051, 2022). "We have previously demonstrated NFATc1 messenger RNA (mRNA) induction in peripheral blood mononuclear cells (PBMCs) in pediatric asthma and that the absence of NFATc1 in T cells results in the downregulation of IL‐4 and other Th2 cytokines and IgE in asthma models." (PMID 33079489, 2020). "In addition to NFATc1 and NIP45, NFATc2 was found upregulated in asthma." (PMID 33079489, 2020).
Burkitt lymphoma (9 papers, 2017 to 2024). A rare form of malignant mature B-cell non-Hodgkin lymphoma. "Knock-down of IRF4 in a T1 LCL (infected with the Zp-V3-containing Akata strain) induced lytic reactivation whereas over-expression of IRF4 in Burkitt lymphoma cells inhibited both NFATc1 and NFATc2 expression and lytic EBV reactivation." (PMID 35472072, 2022). "Furthermore, while NFATc1 inhibits the ability of BCR activation to induce apoptosis in Burkitt lymphoma cells, NFATc2 has the opposite effect." (PMID 32059024, 2020). "Consistently, active NFATC1 and NFATC2 can induce lytic EBV gene expression in EBV positive Burkitt lymphoma cells." (PMID 36383217, 2022). "NFATc1 (also known as NFAT2), a member of the NFAT family, has been detected in tumor samples of B-cell lymphoid neoplasms, including MALT lymphoma, Burkitt’s lymphoma, and Hodgkin’s lymphoma." (PMID 30999581, 2019). "Furthermore, we find that IRF4 over-expression decreases the levels of both NFATc1 and NFATc2 in EBV-positive Burkitt lymphoma cells and inhibits lytic EBV reactivation in response to BCR activation." (PMID 35472072, 2022). "Nevertheless, we cannot exclude the possibility that EBNA2 type-dependent regulation of NFATc1/NFATc2 expression is specific to LCLs and not present in the context of Burkitt lymphoma cells." (PMID 32059024, 2020).
colon cancer (9 papers, 2011 to 2025). "In patients with colon cancer, tumor expression of nuclear NFATc1 was associated with inferior survival while tumor expression of NFATc2 correlated with superior survival." (PMID 26795951, 2016). "Previous studies have established that NFATc1 overexpression is strongly associated with aggressive tumor behavior and poor clinical outcomes in various cancers, including pancreatic, gastric, and colon cancer." (PMID 41203626, 2025). "Consistently, treatment with the NFAT inhibitory peptide VIVIT almost completely abolished SKAP1‐induced CXCL8 expression, suggesting that SKAP1 dependents on NFATc1 to increase CXCL8 expression in colon cancer cells." (PMID 39269257, 2024). "Our findings showed that ENTPD2 was released via exosomes from colon cancer cells to suppress CD8+ T-cell function by both limiting ATP-P2 X7 receptor (P2 X7R)-mediated NFATc1 nuclear transcription and promoting the activity of the adenosine-A2AR pathway." (PMID 38755598, 2024). "In conclusion, SKAP1 significantly promotes colon cancer growth via the cancer cell/neutrophil NFATc1/CXCL8/NET axis, suggesting that SKAP1 is a potential target for colon cancer therapy." (PMID 39269257, 2024). "Consistently, NFAT transcriptional activity contributes to metastasis in colon cancer; inhibition of NFATc1 reduced metastatic growth in an immunocompetent mouse model." (PMID 33014880, 2020). "To determine if these laboratory observations provide clinical insight, we investigated the relationship of NFATc1 and NFATc2 tumor expression and the survival of patients with history of colon cancer." (PMID 26795951, 2016). "In patients with colon cancer, tumor expression of NFATc2 correlated with superior survival, while nuclear NFATc1 with inferior survival." (PMID 26795951, 2016). "This dual regulatory mechanism suggests that pharmacological inhibition of NFATc1 could provide a two-pronged therapeutic approach to suppress colon cancer growth." (PMID 41203626, 2025). "Moreover, NFATc1 mRNA levels were significantly elevated by SKAP1 overexpression in colon cancer cells." (PMID 39269257, 2024). "We provide evidence, for the first time, that SKAP1 expression in cancer cells potently promotes the in vivo growth of colon tumors and further revealed that the cancer cell/neutrophil NFATc1/CXCL8/NET axis is the key mechanism contributing to the tumor‐promoting effect of SKAP1." (PMID 39269257, 2024). "Clinical validation of the SKAP1/NFATc1/CXCL8 axis in colon cancer is also required." (PMID 39269257, 2024). "For example, NFATc1 promotes proliferation of hepatocellular carcinoma cells, NFATc2 increases the invasiveness of breast cancer cells, and NFATc3 and NFATc4 promote the progression of colon cancer." (PMID 28881766, 2017). "Consistent with this, our data showed that NFATc1 expression was detected in nearly all colon cancers in our cohort, and in approximately 50% of these cases NFATc1 was expressed in both nucleus and cytoplasm, and nuclear expression of NFATc1 was associated with worse survival." (PMID 26795951, 2016). "Notably, SKAP1 regulated the transcriptional expression of NFATc1 in colon cancer cells." (PMID 39269257, 2024). "We investigated the correlation between NFATc1 and NADK in clinical colon cancer samples using data from the TCGA database." (PMID 41203626, 2025). "In colon cancer cells, SKAP1 increased the expression of C‐X‐C motif chemokine ligand 8 (CXCL8) via nuclear factor of activated T cells c1 (NFATc1)." (PMID 39269257, 2024). "Colon cancer cell-derived exosomes transfer ENTPD2 as an extracellular ATP scavenger, thus impairing CD8+ T-cell function by inhibiting P2 X7R-mediated NFATc1 activation and promoting the activity of the adenosine-A2AR pathway." (PMID 38755598, 2024).
colon cancer (continued). "NFATC1 plays a central role in inducible transcription of cytokine genes in T cells and was downregulated by arsenic in HCT116, a colon cancer cell line." (PMID 27838757, 2017). "NFATc1 knockdown significantly decreased CXCL8 levels in the supernatants of colon cancer cells, whereas SKAP1 overexpression failed to significantly increase CXCL8 levels after NFATc1 knockdown." (PMID 39269257, 2024). "NFATc2 likely opposes the action of NFATc1, NFATc3, and NFATc4 in colon cancer cells as those tumors lacking NFATc2 expression most likely had a more aggressive clinical course driven in part by the unopposed actions of NFATc1, NFATc3, and NFATc4." (PMID 26795951, 2016). "SKAP1 expression in colon cancer cells significantly promoted neutrophil infiltration and NET formation, which largely contributed to the tumor‐promoting effect of SKAP1, via nuclear factor of activated T cells c1 (NFATc1)‐dependent C‐X‐C motif chemokine ligand 8 (CXCL8) expression." (PMID 39269257, 2024).
colorectal cancer (8 papers, 2018 to 2025). A primary or metastatic malignant neoplasm that affects the colon or rectum. "Further, genes upregulated by NFATc1 significantly correlated with worse clinical outcomes for Stage II and III colorectal cancer patients." (PMID 33014880, 2020). "Finally, we demonstrated that NFATc1 inhibitors suppress colorectal cancer (CRC) growth by targeting the NFATc1/NADK and NFATc1/MDM2 axis and synergize with oxaliplatin." (PMID 41203626, 2025).
B cell lymphomas (7 papers, 2017 to 2024). "In HP strains co-cultured with B cell lymphoma cell lines, CagA was translocated to the nucleus through tyrosine phosphorylation (CagAP−Tyr) and simultaneously dephosphorylated NFATc1, subsequently causing nuclear NFATc1 translocation and stimulating the expression of p-SHP-2/p-ERK/Bcl-xL." (PMID 39558403, 2024). "Our current findings indicate that the nuclear translocation of NFATc1 following CagA tyrosine phosphorylation after HP infection activates NFATc1-dependent genes such as p21 and p27 in both B-cell lymphoma cell lines (MA-1 and OCI-Ly3)." (PMID 39558403, 2024). "NFATc1 can also be activated by the B cell receptor (BCR) and upregulate the IL-10 chemokine to activate the JAK2/STAT3 pathway in B cell lymphoma cells, ultimately inducing PD-L1 expression." (PMID 37138354, 2023). "Here we show that post-transcriptional mechanisms are responsible for the calcineurin (CN) independent constitutive nuclear over-expression of NFATc1 in BL and Eμ-MYC – induced B cell lymphomas (BCL)." (PMID 37546418, 2023). "The NFAT family consists of five cellular transcription factors; NFATc1, expressed in lymphoid tissue, is translocated to the nucleus following T cell receptor and BCR activation, and is constitutively activated in some B cell lymphomas, including the BJAB cell line." (PMID 30052684, 2018).
diabetes (7 papers, 2016 to 2025). "Using LocusZoom, a visualization tool of publically-available GWAS data, we asked if SNPs near human NFATC2 and NFATC1 genes are associated with diabetes-related phenotypes." (PMID 27935966, 2016). "The study found that CML promoted vascular calcification through different pathways in diabetes, including p38 MAPK pathway and the nuclear factor of activated T-cells 1 (NFATc1)." (PMID 40979714, 2025).
glioblastoma (7 papers, 2019 to 2022). The most malignant astrocytic tumor (WHO grade IV). "Studies by Wang and co-authors demonstrated the expression of NFATc1 in U251 glioblastoma cells and linked it to increased invasiveness and migration of cancer cells." (PMID 34443374, 2021). "DYRK1A inhibition or polypeptide derived from DYRK1A‐targeted motif of NFATc1, clearly destabilized NFATc1 protein and impaired glioblastoma migration." (PMID 34309232, 2021). "We found that DYRK1A was highly expressed in glioma and glioblastoma cells, and its expression was positively correlated with that of NFATC1." (PMID 34309232, 2021). "In this study, we demonstrate that glioma tissues and glioblastoma cells with high expression levels of DYRK1A exhibit strong NFATC1 activity, revealing a remarkably positive correlation between DYRK1A and NFATC1." (PMID 34309232, 2021). "Our results are consistent with data generated by the TCGA Research Network showing that NFATc1 and NFATc3 are expressed in higher amount in human glioblastoma samples when compared to normal brain tissue." (PMID 31249342, 2019). "In addition, DYRK1A enhanced the migration ability of glioblastoma cells by activating NFATC1 in vitro." (PMID 35655269, 2022). "For instance, DYRK1A could activate NFATC1 to increase the migration ability of glioblastoma cells, while it could play an important role in maintaining cancer stemness in oral squamous cell carcinoma." (PMID 35655269, 2022). "In conclusion, DYRK1A activated NFATC1 and increased glioblastoma migration." (PMID 34309232, 2021). "Moreover, NFATc1 was found constitutionally active in human glioblastoma samples." (PMID 34443374, 2021). "Polypeptides derived from the DYRK1A‐targeted motif of NFATC1, by competitively blocking DYRK1A kinase activity on NFATC1, clearly destabilized NFATC1 protein and impaired glioblastoma migration." (PMID 34309232, 2021).
lupus (7 papers, 2016 to 2024). "The inhibitor of the serine/threonine kinase Pim-1 “SGI-1776” was identified as a promising therapy, corroborating experimental data which suggest that inhibition of the Pim-1/NFATc1/NLRP3 pathway ameliorates nephritis in lupus mouse models." (PMID 37072752, 2023). "NFATC1 is overexpressed in lupus-prone MRL/lpr mice activating the calcium/NF-AT pathway." (PMID 33915751, 2021). "Next, using purified CD4+ T cells from lupus patients, we also found that HCQ pretreatment significantly decreased NFATc1 expression in activated CD4+ T cells." (PMID 28793932, 2017).
myeloma (7 papers, 2016 to 2024). "Consequently, these results indicated that overexpression of SELENOW in multiple myeloma may be associated with excessive osteoclast differentiation via efficient nuclear translocation of the osteoclastogenic transcription factors NF-κB and NFATc1." (PMID 38683225, 2024). "Excessive expression of SELENOW in osteoclast progenitors and mature osteoclasts derived from multiple myeloma facilitated efficient nuclear translocation of osteoclastogenic transcription factors NF-κB and NFATc1, which are favorable for osteoclast formation." (PMID 38683225, 2024). "Polymorphisms in genes involved in nervous system function, NFATC1, NFATC4, and EDN1 were associated with CIPN in 646 myeloma patients treated with bortezomib, as were TCF4, DYNC1I1, and GJE1 in 139 myeloma patients treated with bortezmib." (PMID 35360655, 2022). "RANKL stimulation in multiple myeloma-derived osteoclasts induced elevated co-translocation of the cytosolic osteoclast-inducing essential transcription factors of NF-κB (p65 subunit) and NFATc1, and SELENOW into the nucleus as compared to that in the control cells." (PMID 38683225, 2024). "In addition, we found that the activation of NCX1 by extracellular high calcium microenvironment increased the osteoclastic activity, indicating that NCX1-induced calcium influx of myeloma cells activates JNK/c-Fos/NFATc1 pathway and modulates RANKL-induced osteoclast differentiation." (PMID 36251145, 2023). "Real time PCR analysis and western blot revealed that monocytes NFATc1 mRNA and proteins levels are higher, IRF8 protein levels are lower treated with myeloma cells exosomes as compared to untreated cells or healthy plasma cell exosomes treated cells." (PMID 36451863, 2022). "These experiments demonstrate that myeloma cells hnRNPA2B1 regulated monocytes IRF8 and NFATc1 or MSCs RUNX2 expression through exosomes miR-92a-2-5p or miR-373-3p." (PMID 36451863, 2022). "Besides, we found a strong positive correlation between the levels of miR-92a-2-5p or miR-373-3p with NFATc1 mRNA, and a strong negative correlation between the levels of miR-373-3p with osterix (RUNX2 target gene) mRNA in myeloma patients." (PMID 36451863, 2022).
autoimmune disease (6 papers, 2015 to 2025). A disorder resulting from loss of function or tissue destruction of an organ or multiple organs, arising from humoral or cellular immune responses of the individual to their own tissue constituents. "NFATc1's dysregulation has been implicated in several autoimmune diseases, where its aberrant activation leads to the inappropriate activation of immune cells and the production of autoantibodies." (PMID 40688507, 2025). "•Pathological relevance: Aberrant NFATc1 and c-Jun activity is implicated in autoimmune diseases, cancer, and chronic inflammation." (PMID 40688507, 2025). "NFATc1 and c-Jun represent promising targets for therapeutic intervention across a spectrum of immune-related diseases, from autoimmune disorders to cancer and chronic inflammation." (PMID 40688507, 2025). "The interplay between NFATc1 activity and IL-10 production is not only restricted to the generation of psoriasis-like symptoms but also involved in other autoimmune diseases." (PMID 27222343, 2016). "It remains a challenging task to elucidate whether the manipulation of NFATc1 and IL-10 activities, alone or together with those of IL-17 and IL-23, will be of benefit for patients suffering from psoriasis and other autoimmune diseases." (PMID 27222343, 2016). "These and further data suggest that the NFATc1-mediated inhibition of IL-10 expression might be of general impact for the development of autoimmune diseases and a novel target how to treat them." (PMID 27222343, 2016). "It is difficult to establish a definitive genotype-phenotype association, but it appears plausible that this proposed autoimmune critical region and PTPN2 on the short arm, as well as NFATc1 on the long arm may play a part in the autoimmune diseases seen in our patient." (PMID 29560252, 2017). "Given the important role of NFATc1 in T-cell activation, the NFAT inhibitor CsA is used as an immunosuppressive agent in graft-vs-host disease (GVHD) and autoimmune diseases." (PMID 25851535, 2015).